IL10 (interleukin 10)
Diseases named in the same sentence as IL10 in open-access papers (continued):
Sharing a sentence is not in itself a finding about the gene and the disease.
colitis (continued). "Experimental evidence supports a role for commensal bacteria in the pathogenesis of IBD; for example, spontaneous colitis develops in mice deficient in interleukin (IL)-2 and IL-10 when colonized with a complex microbiota, but not in mice raised under germ-free conditions." (PMID 24722235, 2014). "Development and remission of DSS-induced colitis in mice was determined by weight measurements and histology scores, and by quantification of expression of pro- (IL-1β, IL-6 and IFNγ) and anti-inflammatory (IL-10) cytokines, the chemokine CXCL1 and the inducible nitric oxide synthase." (PMID 24401855, 2014). "However, it is noteworthy that the reconstitution of IL10/Nox1dKO mice with bone marrow from WT donors could be biased since histological signs of colitis were already present before irradiation and bone marrow transplantation." (PMID 25014110, 2014). "Next, the CX3CL1–CX3CR1 axis has been shown to be required for optimal production of IL-10 by intestinal mφ 56 and finally, CX3CR1-deficiency has been reported to lead to decreased numbers of intestinal mφ 107,108 as well as altering susceptibility to chemically induced colitis." (PMID 24942685, 2014). "In this study, we showed that both immunological and epithelial deficiencies in mice lacking the anti-inflammatory cytokine IL10 and Nox1 sensitized the colon to spontaneously develop severe colitis and mimicked all clinical and histological characteristics of UC." (PMID 25014110, 2014). "However, administration of S. boulardii in animal models has been shown to increase secretory IgA, interleukin 10 (IL-10), and IL-10 induced T regulatory cells as well as to preserve intestinal epithelial integrity in colitis models and to degrade specific pathogen toxins." (PMID 25391025, 2014). "Because it has been reported that the reduction of small intestinal permeability could attenuate the colitis and protect the intestinal barrier function in the IL-10-/- mice, MIMP may alleviate the intestinal inflammation by reducing small intestinal and colonic permeability." (PMID 25277875, 2014). "In addition, the higher levels of IL-10 in the colon may be involved in the protection of CD69 KO mice from severe colitis." (PMID 23785429, 2013). "The aim was to detect and investigate if the effects of IL-10 on prohibitin has antifibrotic effects and prevents the progression of intestinal fibrosis in the IL-10KO mice model of CD and to determine the role of prohibitin in intestinal fibrosis of murine colitis." (PMID 23690666, 2013). "In this paper we investigate how oral administration of very low doses of the anti-inflammatory cytokine IL-10 and an antibody raised against the pro-inflammatory cytokine IL-1 alpha confers protection against experimentally-induced inflammation in a mouse model of colitis." (PMID 27785242, 2013). "Based on these features, the histology of colitis in TNF-deficient T/I mice (and TNF-haplo-insufficient T-het/I mice) closely resembled what is typically seen in human UC, while colitis in mice singly deficient in IL-10 more closely resembled that seen in human CD." (PMID 22848611, 2012). "Moreover, IL-10 secreted by CD11b+CD11c+ dendritic cells is a fundamental cytokine for the maintenance of Foxp3 expression in induced regulatory T cells in the periphery during colitis development." (PMID 22400037, 2012). "IL-10−/− mice can develop a spontaneous colitis by 12 wks of age and though we used young IL-10−/− mice (<10 wks), we wanted to confirm our findings and rule out secondary adverse effects due to congenital IL-10-deficiency." (PMID 22393401, 2012). "Although mice with deletion of the gene that encodes IL-10 were originally reported to spontaneously develop colitis, we have found that Il10−/− mice on the C57BL/6 background are resistant to the development of spontaneous colitis when kept free of pathogens such as Helicobacter." (PMID 22848611, 2012).
colitis (continued). "Moreover, we recently showed that in a model of colitis-associated colon cancer, B. vulgatus failed to promote tumor development in IL-10−/− mice whereas numerous adenomas are present in conventionalized- IL-10−/− mice." (PMID 19841748, 2009). "It alleviates DSS-induced colitis by activating aryl hydrocarbon receptor (AhR) signaling and promoting FOXP3+ Treg differentiation, and reduces pro-inflammatory NF-κB activity in IL-10-/- mice through a pirin-like protein." (PMID 41572837, 2026). "Our group previously discovered that crossing PAK1KO with IL10 knockout (IL10KO) mice, a mouse model that develops spontaneous colitis, resulted in a hyperproliferative phenotype with increased inflammation and tumorigenesis." (PMID 40783411, 2025). "The results showed that oral tCA-GA administration led to an increase in IL-10 levels in colitis, whereas co-administration of MPZ significantly decreased IL-10 levels in the inflamed colon of rats." (PMID 40872532, 2025). "Deletion of EGFR in macrophages in DSS-colitis mice leads to the increase of anti-inflammatory cytokines, such as IL-10 that inhibits the release of proinflammatory cytokines such as IL-6, IL-8 and TNF, limiting colitis development." (PMID 39966897, 2025). "Matrix metalloproteinase (MMP)-10, IL-17A, FGF-19, IL-10, and CXCL9 were increased in patients with exclusive colonic inflammation, that is, UC and colonic CD, compared to patients with exclusive ileal inflammation, that is, ileal CD." (PMID 39495605, 2025). "In summary, our studies demonstrate that DCA promotes a metabolic program that regulates T cell production of IL-10 and IL-22, and that DCA treatment inhibits colitis development." (PMID 41321963, 2025). "The expression of colitis‐related genes, including COX‐2, TNF‐α, IL‐6, and IL‐10, was detected in the colon using RT‐qPCR." (PMID 39803293, 2025). "By performing in vivo calcium imaging on DSS-colitis mice at peak disease, we found a reduction in the amplitude of mean TNF and IL-10 responses in the DSS group when compared to controls." (PMID 40268933, 2025). "Thus, while the specific relationship between intestinal clock and colitis development in IL-10-/- mice remains unclear, a better understanding of the compositional and rhythmic microbiome changes that precede colitis symptoms may help to identify predictive markers for disease development." (PMID 39843997, 2025). "ERK activation has been shown to increase interleukin-10 (IL-10) secretion and alleviate DSS-induced colitis by promoting ERK phosphorylation." (PMID 40452925, 2025). "Pre-treatment with recombinant TIMP-1 of mice with experimental colitis reduced the mucosal pathology while splenocytes from pretreated mice produced less TNF-α and more IL-10 than untreated mice following stimulation with anti-CD3." (PMID 40565065, 2025). "Collectively, our observations suggest that STING signaling is required to generate the antiinflammatory cytokine IL-10 in myeloid cells after LGG administration and plays a role in maintaining gut immune homeostasis in colitis." (PMID 39895628, 2025). "This review indicated that IN alleviates colitis by activating AhR signaling and inhibiting STAT1/STAT3 signals and IL-10." (PMID 40756994, 2025). "In our study, we also found that the IEC-specific deletion of STAT3 (Villin-Cre STAT3fl/fl) reduced the secretion of anti-inflammatory cytokines IL-10 and IL-22 and augmented epithelial erosions and mucosal barrier disruption after DSS-induced colitis." (PMID 39773987, 2025). "IL-10 inhibits Th1-related cytokine production by suppressing antigen-presenting cells, while TGF-β1 modulates antigen-specific T-cells to prevent colitis." (PMID 39861171, 2025). "Bacteroides thetaiotaomicron bEVs carry surface polysaccharides that promote IL-10 production in DCs and regulatory T cells via TLR2/Gadd45α signaling and demonstrate protective effects in murine acute colitis models by maintaining intestinal homeostasis." (PMID 41025638, 2025).
colitis (continued). "Using a State-of-the-Art whole-body small-animal PM2.5 inhalation exposure system, we examined the impacts of PM2.5 on gut inflammation and the mucous barrier in IL-10 knockout (IL10−/−) mice, a widely used mouse model for spontaneous colitis." (PMID 40868077, 2025). "In colitis mice, the CCFM1426 and VA combination significantly reduced IL-6 and TNF-α levels whilst increasing IL-10 levels (p < 0.05)." (PMID 40777179, 2025). "Peptidoglycan from L. salivarius Ls33 was shown to protect BALB/c mice against colitis through NOD2 receptor activation, resulting in elevated colonic IL-10 levels and increased Treg cells in the mesenteric lymph nodes, even with oral administration." (PMID 41301527, 2025). "The anti-inflammatory effect of probiotics has been confirmed TNF-a, IFN-γ, IL-10, and IL-1β in the DSS-induced colitis mouse model." (PMID 40219015, 2025). "The restoration of IL-10 and TGF-β levels through synbiotic treatment is especially significant for achieving long-term therapeutic outcomes in colitis." (PMID 40195063, 2025). "Further studies have demonstrated that NLRP3 deficiency downregulates glucose transporter protein 1 (GLUT1) expression and glycolytic activity in MSCs, leading to decreased IL-10 production and reduced therapeutic efficacy against DSS-induced colitis." (PMID 40433382, 2025). "This subset upregulated IL-10 expression and significantly inhibited the secretion of inflammatory cytokines by T cells, thereby improving TNBS-induced colitis in mice." (PMID 40433382, 2025). "The most popular models of colitis include chemical induction (oxazolone, TNBS, DSS), adoptive T‐cell transfer in SCID or RAG2‐/‐ mice, IL‐10 knockout mice, and the SAMP1/YitFc mouse strain (spontaneous colitis model)." (PMID 40457749, 2025). "A bifunctional PGH named LPH, derived from lactobacilli, attenuated TNBS-induced colitis in mice by digesting PGN and releasing NOD2 ligands, thereby increasing IL-10 and decreasing TNF-α, IFN-γ, and IL-6, exerting an anti-inflammatory activity." (PMID 41301527, 2025). "L. johnsonii activates primary macrophages into CD206+ macrophages that release IL-10 via the TLR1/2-STAT3 pathway, thereby mitigating experimental colitis." (PMID 40292216, 2025). "Therefore, colitis reported in these animals might be caused by the loss of Treg cell-derived IL-10 during a critical developmental window rather than its continuous production by a specialized colonic population." (PMID 39905200, 2025). "The UC group showed severe colitis, increased TNF‐α and IL‐6, decreased IL‐10, elevated TOC, reduced TAC, altered VEGF/EGF mRNA, PI3K/AKT activation, and increased apoptosis (Bax/Bcl‐2 ratio, Cytochrome c, Caspase‐9, Caspase‐3)." (PMID 40688608, 2025). "For example, strain ZDY2013, when combined with isomaltooligosaccharides, enhances the expression of MUC2, tight junction proteins (ZO-1, claudin), and cytokines such as IL-10 and IL-22 in DSS-induced colitis models." (PMID 41141596, 2025). "The PPARα agonist fenofibrate, a lipid-lowering drug, improves colitis by reducing IL-17 and IFN-γ production by Th1 and Th17 cells in IL-10 -/- KO mice, a murine model of IBD." (PMID 39451206, 2024). "In the 2% DSS-induced colitis-mouse model, Trp administration (100 mg/kg) led to a significant decrease in TNF-α and increase in IL-10 in the serum as well as a significant decrease in the inflammation score." (PMID 38542428, 2024). "Various colitis symptoms in mice, including body weight, thymus index, spleen index, IL-6, TNF-α, IL-1β, IL-10, and IgA, were restored with 100 mg/kg PSPRS and 300 mg/kg PSPRS administration." (PMID 38611336, 2024). "HucMSC prevents experimental colitis by increasing the number of CD5+ B cells and CD5+Bregs that produce IL-10, and restores Treg/Th17/Th1 imbalances." (PMID 39185411, 2024). "Bifidobacterium adolescentis ameliorated DSS-induced colitis by reducing TNF-α, IL-1β, and IL-6 levels and increasing IL-10 and IL-4 levels." (PMID 38540864, 2024).
colitis (continued). "In the acute colitis model, we initially aimed to assess the impact of DSS on anti-inflammatory cytokines as well, particularly IL-10, given its pivotal role in immune regulation." (PMID 39682761, 2024). "Thus, H2S may cause mucus disruption by reducing its disulfide bonds, and the administration of the H2S-producing bacterium Desulfovibrio indonesiensis and Atopobium parvulum exacerbates the development of TNBS colitis and spontaneous colitis in Il10−/− mice, respectively." (PMID 39427081, 2024). "Quercetin can alleviate inflammation by reducing the levels of TNF-α, IL-1β, IL-6, and IL-10, thus treating DSS-induced colitis in mice." (PMID 38902425, 2024). "In the current investigation, the treatment of TNBS-induced colitis with both mesalazine and AL0035 significantly increased the expression of IL-10, which is reported to be a critical point for the decrease in gut inflammation." (PMID 38612971, 2024). "For example, after induction of colitis in mice, intraperitoneal injection of MSC-CM significantly increases the levels of IL-10 and TGF-β in mesenteric lymph nodes and the spleen, elicits anti-inflammatory effects, and reduces colitis and mortality." (PMID 37588208, 2024). "Accordingly, in a rodent model of disease, CD30L−/− mice appear resistant to chemical colitis due to impaired expression of multiple cytokines including IFN-γ, IL-17A, and IL-10." (PMID 38903247, 2024). "Cytokine plasma levels currently used to monitor DSS colitis (TNFα, IL6, IL10 and IL17) were dosed at 3 (baseline) and 5.5 months to evaluate systemic inflammation." (PMID 38773640, 2024). "L. plantarum HNU082 and B. adolescentis also attenuated the inflammatory response in a DSS-induced colitis by downregulating TNF-α and IL-1β while upregulating IL-10." (PMID 37639209, 2024). "In Il10−/− Il17a−/− mice, the high concentration of MDSC-expressed NO induced the barrier disruption of gut microbiota and exacerbated the pathology of the colitis." (PMID 37733169, 2024). "Specifically, the levels of TNF-α, IL-1β, IL-6, IL-10, IL-2, and IL-12 SOD, CAT, GSH-Px, and MDA were modulated in rats with colitis, also inhibiting TLR4/NF-κB pathway activation." (PMID 39494333, 2024). "This aspect warrants a separate study to address the pathological implications of early RSV infection, particularly in the context of colitis inflammatory disease models, such as the dextran sulphate sodium (DSS) model or the IL-10 knockout mouse model." (PMID 39451246, 2024). "B. thetaiotaomicron was found to ameliorate the severity of colitis model in dextran sodium sulfate (DSS) and interleukin (IL)-10 knockout models of colitis." (PMID 38502145, 2024). "For instance, LD IL-10 and anti-IL1-α antibodies demonstrate promise in colitis and osteoarthritis models, while a combination of IL-4, IL-10, and anti-IL1-α antibodies outperforms DMARDs in rheumatoid arthritis." (PMID 38792574, 2024). "Indigo Naturalis (IN) notably improved colitis in mice by enhancing colon tissue structure, reducing pro-inflammatory cytokines (IL-6, IL-8, TNF-a), and increasing anti-inflammatory cytokine IL-10." (PMID 39411430, 2024). "HFD feeding resulted in colitis: it elevated myeloperoxidase, TNF-α, IL-1β, and IL-6 levels, NF-κB activation (p-p65/p65), and NF-κB+CD11c+ cell number and decreased IL-10 and SIRT1 levels and AMPK activation (p-AMPK/AMPK) in the colon." (PMID 39599597, 2024). "Further investigations revealed that UDCA increased the expression of IL-10 and TGF-β in colitis and promoted Treg cell differentiation in vitro." (PMID 38292253, 2024). "For example, in a model of NSAID-induced colitis, NK1R expression was induced in T lymphocytes of IL-10 knockout animals." (PMID 38221552, 2024). "Treatment of DCs with PSA-containing MVs prevented trinitrobenzene sulfonic acid (TNBS)-induced colitis in mice via suppression of the proinflammatory cytokines, TNF-α and IL-17, and increased secretion of IL-10." (PMID 38666762, 2024).
colitis (continued). "Stard7+/– mice were mated with Il10–/– mice on C57BL/6 background and monitored for the development of the spontaneous colitis phenotype." (PMID 39576011, 2024). "The AhR antagonist StemRegenin 1 essentially abrogated the ameliorative effect of 5HIAA on colitis, as reflected by body weight, DAI, colon length, serum levels of IL‐22 and IL‐10, and colon histology." (PMID 38882491, 2024). "Strains that induced higher levels of the anti-inflammatory cytokine IL-10 and lower levels of pro-inflammatory cytokines such as IL-1β, IL-6, interferon γ (IFNγ), and TNF-α offered protection in induced colitis." (PMID 39767038, 2024). "Eventually, Zhou and collaborators discovered that IL-10 concentrations in the blood and tissues of mice with DSS-induced colitis declined to various degrees but rose in serum and colon tissues following L. fermentum CQPC04 treatment." (PMID 39323474, 2024). "It has been shown, that Tr1 cells inhibit the proliferation of antigen-specific T cells through an IL-10-dependent mechanism and exhibit protective effects in the adoptive transfer model of colitis involving naïve T cells, as in SCID patients with colitis." (PMID 38507159, 2024). "In this study, after administering Ento-PB to rats with OXZ-induced colitis, the expression levels of IL-13 and TNF-α significantly decreased, while the expression levels of IL-4, IL-10, and EGF sharply increased." (PMID 39230095, 2024). "A previous study using a colitis animal model has shown that exercise reduces pro-inflammatory cytokines TNF-α and IL-1β expression, increases anti-inflammatory cytokine IL-10 expression, and reduces stress-induced barrier dysfunction." (PMID 38791116, 2024). "We estimated the effect of XYKJP on inflammatory cytokines in colitis tissues and found that XYKJP treatment led to a reduction in the levels of IL-1β, TNF-α, and IL-6, and a significant improvement in the level of IL-10 and IL-22, as demonstrated by ELISA." (PMID 39133435, 2024). "Anti-inflammatory cytokines (such as IL-4, IL-10, IL-22, etc.)can inhibit the proliferation of TH17 and TH2 cells and intestinal wall disorders, thus alleviating colitis in mice." (PMID 37240380, 2023). "EVs from broccoli proved to improve colitis by reducing the expression of TNF-α, IL-17, and IFN-γ while decreasing IL-10." (PMID 38201294, 2023). "The repercussion of colitis on the hepatic inflammatory profile was investigated, through MPO activity and TNF-α and IL-10 levels." (PMID 37577725, 2023). "Administration of IPA attenuates pro-inflammatory (CD4+IFNγ+IL10−) T cells and increases anti-inflammatory (CD4+IFNγ−IL10+) T cells in the colon in a mouse model of colitis." (PMID 37298145, 2023). "L. johnsonii improved experimental colitis by promoting the conversion of native macrophages into CD206+ macrophages and releasing IL-10 via the TLR1/2-STAT3 pathway." (PMID 37485519, 2023). "For instance, LNPs‐mediated delivery of IL‐10 mRNA can promote the expression of IL‐10 in inflammatory leukocytes and attenuate the dextran sodium sulfate (DSS)‐induced colitis in experimental mouse." (PMID 37206219, 2023). "In contrast, several studies investigating hepatic tissue in colitis induction models with 3%, 4%, and 5% DSS reported increased levels of TNF-α and/or MPO activity and similarly to our work reduced levels of IL-10." (PMID 37577725, 2023). "These mice exhibited increased bacterial content in intestinal mucosa, and when bred with global Il10−/− mice on a C57BL/6 background for at least eight generations, they exhibited accelerated colitis." (PMID 37059333, 2023). "IL-10 can suppress the secretion of pro-inflammatory cytokines, such as TNFα, to improve colonic inflammation in the DSS-induced colitis model." (PMID 37185924, 2023). "IL-10 gene delivery can prevent trinitrobenzene sulfonic acid (TNBS) and dextran sodium sulfate (DSS)-induced murine colitis." (PMID 37375032, 2023).